ATF4 (activating transcription factor 4)
Diseases named in the same sentence as ATF4 in open-access papers (continued):
Sharing a sentence is not in itself a finding about the gene and the disease.
melanoma (continued). "It displays strong anti-tumorigenic activity in xenograft mouse models with melanoma cells, which depends on activation of ATF4 and DDIT3, without toxicity in normal cells." (PMID 29290987, 2017). "For instance, a recent paper showed that induction of ATF4 in melanoma cell lines inhibits MITF expression, but does not affect invasive potential." (PMID 28545079, 2017). "Similarly, expression of the PERK pathway down-stream targets ATF4 and CHOP was negatively correlated with survival and CHOP expression was elevated in melanoma compared to nevi samples." (PMID 29235576, 2017). "Indeed, melanoma cells rely on GCN2/eIF2α axis to induce the expression of receptor tyrosine kinases (RTKs), which initiates a signaling cascade through MAPK/mTORC1/eIF4E axis to achieve maximal induction of ATF4." (PMID 34205460, 2021). "However, the GCN2/eIF2α feedback loop seems not to be sufficient to induce the ATF4 in melanoma cells to mediate adaptation." (PMID 34205460, 2021). "ACF can induce a decrease in MITF expression in melanoma cells even in the absence of ATF4." (PMID 33396270, 2020). "The missing of GRP78/94 upregulation suggests that the NGLY1 suppression-induced activation of ATF4 and GADD153 in melanoma cells may not be directly caused by ER stress." (PMID 30385822, 2018). "Moreover, depletion of ATF4 using RNAi technology prevented the reduction in MITF expression in response to glucose restriction, clearly demonstrating that ATF4 acts as the link between glucose metabolism and MITF in melanoma cells." (PMID 28380427, 2017). "In addition, and contrary to previous reports, we do not observe an induction of ATF4 in melanoma cells under hypoxic conditions." (PMID 28380427, 2017). "Collectively, these results indicate that ACF is likely to decrease MITF levels in melanoma cells by modulating the phosphorylation of ERK1/2 and CREB in a mechanism independent of ATF4." (PMID 33396270, 2020). "In agreement, we observed that the ACF-dependent decrease of ATF4 protein in SK-MEL-28 cells was not accompanied by a concomitant decrease in ATF4-mRNA levels; instead, ACF increased the levels of ATF4-mRNA in this melanoma cell line." (PMID 33396270, 2020). "Although ATF4 and GADD153 were upregulated in NGLY1-knockdown melanoma cells, we did not observe a clear upregulation of ER chaperones GRP78/94." (PMID 30385822, 2018). "Mechanistically, c-MYC has been reported to mediate PI induction of NOXA in melanoma cells, whereas NOXA transcription can also be regulated by ATF3/ATF4 in the non-PI setting through a variety of signaling pathways, including the endoplasmic reticulum stress pathway." (PMID 39302104, 2024).
glioma (62 papers, 2012 to 2025). A benign or malignant brain and spinal cord tumor that arises from glial cells (astrocytes, oligodendrocytes, ependymal cells). "Considering that ATF4 transcriptionally regulates multiple genes associated with cancer, we planned to explore Sev-associated ATF4-regulated genes in glioma cell ferroptosis." (PMID 35372041, 2022). "Analyses of databases suggested elevated ATF4 expression in gliomas in comparison to normal brain tissue and an association of increased ATF4 transcription with poor overall survival in glioma cohorts." (PMID 34239013, 2021). "Similarly, ATF4 knockdown increased the susceptibility to ferroptosis in glioma cells treated with erastin and sorafenib." (PMID 40227255, 2025). "Similarly, the activation of the eIF2α-ATF4 pathway is implicated in promoting ferroptosis in various cell types, including glioma cells, cardiomyocytes, and prostate cancer cells." (PMID 40227255, 2025). "It has been found that reducing the expression of the cellular stress response factor ATF4 diminishes System xc− activity and makes human glioma cells more susceptible to ferroptosis, suggesting that the ATF4-System xc− pathway may be an additional mechanism by which ERS affects ferroptosi." (PMID 39199307, 2024). "The published article titled “Overexpression of miR-1283 Inhibits Cell Proliferation and Invasion of Glioma Cells by Targeting ATF4” has been retracted from Oncology Research, Vol." (PMID 41179302, 2025). "Conversely, NF-κB pathway activation in GPX4 knocked-down glioma cells decreased ATF4 and SLC7A11 expression and significantly increased the occurrence of ferroptosis." (PMID 38539832, 2024). "ATF4 promoted glioma cell proliferation and glutamate secretion through xCT regulation in U87 and U251 cells." (PMID 38601083, 2024). "There were 5 ferroptosis-associated genes (KEAP1, NFE2L2, NOX4, ATF4, ASCL4) that have been tested in human glioma with different research methods." (PMID 36627482, 2023). "ATF4 is described as a chemoresistance gene in gliomas, because its high expression promotes glioma resistance to TMZ." (PMID 35805884, 2022). "Silencing P2X4R interrupts the proliferation of glioma cells by downregulating the BDNF/TrkB/ATF4 pathway." (PMID 35372041, 2022). "Activating transcription factor 4 (ATF4) can increase neovascularization within gliomas and shape neovascularization in a SLC7A11-dependent manner." (PMID 36185243, 2022). "In order to reveal the exact pathway of ferroptosis induced by Sev in glioma cells, we selected differentially expressed genes and found that the fold change of ATF4 was the second increased." (PMID 35372041, 2022). "According to Sev transcriptional sequencing, the expression of ferroptosis- and mitophagy-related gene-activating transcription factor 4 (ATF4) was enhanced, and Sev induced ferroptosis in glioma cells by activating the ATF4-CHAC1 pathway." (PMID 36313359, 2022). "Dihydroartemisinin (DHA) can activate ATF4 by promoting the level of p-ERK in glioma cells, thereby increasing the level of heat shock protein family A (Hsp70) member five HSPA5." (PMID 35784729, 2022). "Ferroptosis inducer Erastin was used to incubate glioma cells combined with Sev and ATF4 siRNA transfection treatment." (PMID 35372041, 2022). "Our data showed that induction of ferroptosis reversed ATF4 suppression-mediated effects on Sev-induced proliferation, iron accumulation, and ROS accumulation in glioma cells." (PMID 35372041, 2022). "HSPA5 has the effect of up-regulating the GPX4, which results in protecting glioma cells from ferroptosis, indicating the activation of ATF4 strengthens the drug resistance of glioma." (PMID 35784729, 2022). "ATF4 expression was found elevated in the malignant types of gliomas and in the high-grade tumors correlated with poor overall patient survival." (PMID 35409080, 2022). "The xCT pathway mediated by ATF4, lastly, confers glioma tumor resistance towards chemotherapy with TMZ." (PMID 35409080, 2022).
glioma (continued). "The other evidence that ferroptosis influences glioma angiogenesis has been derived from studies of the transcriptional activator ATF4." (PMID 36091118, 2022). "ATF4 has also been found to mediate the therapeutic resistance of temozolomide to glioma by upregulating SLC7A11 to absorb more cystine, promote the synthesis of glutathione, and neutralize reactive oxygen species." (PMID 35864117, 2022). "The anti-glioma chemotherapeutic temozolomide has been reported to increase ATF4 expression as a consequence of UPR induction." (PMID 34239013, 2021). "In this study, we found that ER stress marker proteins GRP78, PERK, and ATF4 were all upregulated in brucine-treated glioma cells." (PMID 34112960, 2021). "ATF4 was described as a negative regulator of ferroptosis in glioma cells and its forced expression in hepatoma cells induced protection from ferroptosis." (PMID 34069743, 2021). "The tumorigenic functions of ATF4 are further confirmed by its overexpression in glioma cells, which induces high levels of xCT expression leading to an increase in glutamate secretion." (PMID 33430127, 2021). "Glioma strongly expresses PERK, ATF4, ATF6, IRE1, and XBP1, and is associated with the malignant phenotype and poor prognosis." (PMID 33920356, 2021). "In brief, these findings indicate that ATF4 can affect glioma ferroptosis and TMZ resistance by regulating the expression of SLC7A11." (PMID 32656078, 2020). "Mechanistically, DHA caused endoplasmic reticulum (ER) stress in glioma cells, which resulted in the induction of HSPA5 expression by protein kinase R-like ER kinase (PERK)-upregulated activating transcription factor 4 (ATF4)." (PMID 31519193, 2019). "Our data are the first showing ATF4 protein expression in a large GBM patient dataset, and are in line with a recent report showing that low ATF4 transcript levels in the NIH Rembrandt Glioma database is associated with prolonged survival." (PMID 31534165, 2019). "First, we investigated the expression levels of ATF4 in primary astrocytes and human glioma cell lines." (PMID 28881638, 2017). "In this study, we investigated the temozolomide effects on human gliomas with concomitant ATF4 expression." (PMID 28881638, 2017). "Increased ATF4, Nrf2 and xCT expression levels were detected in human glioma cells subsequently TMZ treatment for 48 h." (PMID 28881638, 2017). "To determine the contribution of ATF4 to the TMZ resistance of human gliomas, we next investigated the gene expression response following TMZ application." (PMID 28881638, 2017). "Altogether, these results evidence that ATF4 is a potent promoter for glioma proliferation and glioma cell motility." (PMID 28881638, 2017). "Our data show that ATF4 operates as a chemo-resistance gene in gliomas, and the tumor promoting function of ATF4 is mainly determined by its transcriptional target xCT." (PMID 28881638, 2017). "Conversely, ATF4 suppression by small interfering RNAs (ATF4KD) leads to increased TMZ susceptibility and autophagy in comparison to wild type gliomas." (PMID 28881638, 2017). "ATF4 overexpression (ATF4OE) fosters TMZ resistance in human gliomas and inhibits TMZ-induced autophagy." (PMID 28881638, 2017). "Activating transcription factor 4 (ATF4) is a critical oxido-metabolic regulator in gliomas, and its role in the pathogenesis of TMZ-resistance remains elusive." (PMID 28881638, 2017). "We monitored cell survival, ATF4 mRNA expression of ATF4 and xCT (SLC7a11) regulation within human gliomas." (PMID 28881638, 2017). "As we demonstrated that TMZ adversely affects glioma cell proliferation and survival, we further explored the contribution of ATF4 to migration and invasion under control conditions and after TMZ treatment." (PMID 28881638, 2017). "Further, cannabinoid-mediated apoptosis is associated with the upregulation of ATF4, DDIT3, and TRIB3 in cannabinoid-sensitive glioma cells." (PMID 29290987, 2017).
glioma (continued). "We found that ATF4 overexpressing tumors are in particular resistant to state-of-the-art multimodal chemotherapeutics for gliomas." (PMID 28881638, 2017). "In contrast, LC3 puncta were undetectable in ATF4OE U87 cells, indicating ATF4 inhibits TMZ-induced autophagy in glioma cells." (PMID 28881638, 2017). "To investigate the association between resistance to TMZ and ATF4 expression in glioma cells, we inhibited ATF4 expression by applying ATF4 specific shRNAs and created ATF4 overexpression by transfecting with vector containing ATF4 wildtype cDNA." (PMID 28881638, 2017). "Both 2OHOA and palmitate (150 μM; 24 h) induced a significant increase in ATF4 gene expression in 1321N1 cells, further demonstrating the specificity of 2OHOA against glioma cells." (PMID 23133576, 2012). "In addition, glutamate antiporter xCT/SCL7A11 has been identified as a downstream target of ATF4 in gliomas." (PMID 38601083, 2024). "Thus, ATF4 ablation is a promising target for suppressing growth and vasculature of gliomas by sensitizing glioma cells to ferroptosis." (PMID 38601083, 2024). "Additionally, ATF4-mediated SLC7A11 upregulation in human glioma cells has been related to ferroptosis resistance." (PMID 36644574, 2023). "Similarly, dihydroartemisinin induced ferroptosis in glioma cells through the PERK/ATF4/HSPA5 pathway." (PMID 36644574, 2023). "Thus, ATF4 can be regarded as a chemo-resistance gene in gliomas being determined by its transcriptional target xCT." (PMID 37554158, 2023). "In our study, Sev induced the expression of CHAC1 in glioma cells, and this effect could be attenuated by inhibiting ATF4 expression." (PMID 35372041, 2022). "Based on this evidence, we might speculate that Sev suppressed the proliferation of glioma cells by ATF4-mediated ferroptosis." (PMID 35372041, 2022). "In some studies, suppression of ATF4 could inhibit cell proliferation and metastasis of glioma cells." (PMID 35372041, 2022). "In addition, activation of PERK/ATF4/HSPA5 pathway attenuated dihydroartemisinin-induced ferroptosis in glioma cells." (PMID 36591279, 2022). "The reason of ATF4 playing a dual role in glioma is unclear." (PMID 35372041, 2022). "In addition, colony formation assays demonstrated that ATF4 expression promotes glioma cell proliferation and migration." (PMID 35409080, 2022). "In addition, glutamate secretion and ATF4-mediated function of xCT represent a candidate mechanism for the promotion of angiogenesis in ATF4 overexpressing gliomas, besides the induction of VEGF and HIF-1α expression." (PMID 35409080, 2022). "Indeed, as a consequence of xCT overexpression, glioma cells become resistant to xCT inhibitors such as sorafenib and erastin, and these effects are reversed upon ATF4 knockdown." (PMID 33430127, 2021). "The potential molecular mechanism of Withaferin A in glioma may be exerted by NF-KB nuclear translocation, activation of caspase cascade and activating transcription factor 4(ATF4)-ATF3-CHOP axis." (PMID 34164339, 2021). "Studies have shown that glioma patients with a high expression of ATF4 have a shorter survival time, and ATF4 can inhibit the ferroptosis of glioma cells by regulating the expression of the downstream gene SLC7A11, in order to promote tumor proliferation and angiogenesis." (PMID 32656078, 2020). "Further research has revealed that the TMZ treatment of glioma cells led to the increase in ATF4 expression, the overexpression of ATF4 can enhance the glioma cells resistance to TMZ, and the inhibition of ATF4 expression can increase the sensitivity of glioma cells to TMZ." (PMID 32656078, 2020). "Since PERK/ATF4 signaling mediated DHA-induced UPR in glioma cells, we investigated whether PERK/ATF4 inhibition enhanced anticancer activity of DHA through ferroptosis induction." (PMID 31519193, 2019).
glioma (continued). "In contrast, overexpression of HSPA5 inhibited DHA-induced ROS, MDA and lipid ROS generation and cell death in glioma cells, suggesting that ATF4-induced HSPA5 might antagonize the pro-ferroptotic activity of DHA." (PMID 31519193, 2019). "Furthermore, inhibition of PERK, ATF4 or HSPA5 enhanced cytotoxic effects of DHA on glioma cells both in vivo and in vitro." (PMID 31519193, 2019). "Since HSPA5 is a master chaperone that could be upregulated by ATF4 during ER stress, we examined the impact of ATF4 knockdown on HSPA5 expression in DHA-treated glioma cells." (PMID 31519193, 2019). "In addition, silencing of ATF4 by siRNA showed similar synergistic pro-ferroptotic effects with DHA in glioma cells, as indicated by enhanced ROS, MDA and lipid ROS production as well as cell death." (PMID 31519193, 2019). "The sensitivity of glioma cells to TMZ was significantly increased following ATF4 siRNA knockdown." (PMID 28881638, 2017). "We detected the expression levels of ATF4 in ATF4-modulated glioma cells by real time PCR." (PMID 28881638, 2017). "To observe whether ATF4 is responsible for TMZ-induced cell death in glioma cells, we analyzed cell death by propidium iodide (PI) staining after TMZ treatment." (PMID 28881638, 2017). "Therefore, therapeutic inactivation of ATF4 can be a promising strategy to overcome chemo-resistance and promote drug efficacy in human gliomas." (PMID 28881638, 2017). "In human U251 gliomas the ATF4 expression was significantly elevated after 400 μM SAS application." (PMID 27074570, 2016). "Hence, we performed ATF4 expression analyses to examine the ER stress response of glioma cell lines under SAS treatment." (PMID 27074570, 2016). "Along with relatively overexpressed ER residents and chaperones, we also noted high levels of UPR activators and effectors Among those effectors is ATF4, which has been identified by others as a highly expressed transcription factor in patient gliomas compared to normal brain." (PMID 24039668, 2013). "Notably, Activating Transcription Factor 3 (ATF3) enhances glioma cell ferroptosis by promoting hydrogen peroxide and iron accumulation, whereas Activating Transcription Factor 4 (ATF4) triggers ferroptosis through Solute Carrier Family 7 Member 11 (SCL7A11)/SCX-dependent mechanism." (PMID 39857625, 2024). "Inactivation of ATF4 might be a key strategy to eliminate chemo-resistance in human gliomas." (PMID 37554158, 2023). "Dihydroartemisinin could attenuate ferroptosis via the PERK/ATF4/HSPA5 pathway in glioma cells." (PMID 35372041, 2022). "RAC1 expression has previously been linked to transcription factor expression in glioma, and while the RNAseq data presented did not link ATF4 and XBP1 to RAC1 expression, the association may depend on cell type and genetic background." (PMID 29329780, 2018). "Additional studies have demonstrated that the ATF4-induced expression of HSPA5, also known as BiP, can prevent GPX4 degradation and protect against ferroptosis in pancreatic ductal adenocarcinoma and glioma cells." (PMID 40227255, 2025). "On the one hand, ATF4 can drive sorafenib resistance in HCC by inhibiting ferroptosis; on the other hand, sevoflurane has been shown to induce ferroptosis of glioma cells through ATF4 activation." (PMID 37488128, 2023). "ATF4 promotes the expression of GSH and SLC7A11 to avoid ferroptosis in glioma cells, inhibition of ATF4 can reduce the resistance of glioma cells to TMZ." (PMID 36072803, 2022). "As another cannabinoid-triggered upstream ion channel a recent investigation found TRPV4 and a signalling pathway including ATF4, DNA Damage Inducible Transcript 3 (DDIT3), TRB3, Akt and mTOR as mediators of CBD-induced mitophagy in glioma cells." (PMID 35277658, 2022). "Inhibitors of autophagy (3-MA or CQ) or knockdown of ATF4 and other related genes were shown to switch the status of FKB-induced senescence to FKB-induced apoptosis in glioma cells." (PMID 35409080, 2022).